ATP5F1A (ATP synthase F1 subunit alpha)
Description:
Subunit alpha, of the mitochondrial membrane ATP synthase complex (F(1)F(0) ATP synthase or Complex V) that produces ATP from ADP in the presence of a proton gradient across the membrane which is generated by electron transport complexes of the respiratory chain (Probable). ATP synthase complex consist of a soluble F(1) head domain - the catalytic core - and a membrane F(1) domain - the membrane proton channel. These two domains are linked by a central stalk rotating inside the F(1) region and a stationary peripheral stalk. During catalysis, ATP synthesis in the catalytic domain of F(1) is coupled via a rotary mechanism of the central stalk subunits to proton translocation (Probable). In vivo, can only synthesize ATP although its ATP hydrolase activity can be activated artificially in vitro (By similarity). With the catalytic subunit beta (ATP5F1B), forms the catalytic core in the F(1) domain. Subunit alpha does not bear the catalytic high-affinity ATP-binding sites (Probable). Binds the bacterial siderophore enterobactin and can promote mitochondrial accumulation of enterobactin-derived iron ions.
Synonyms: ATP5A; ATP5A1; ATP5AL2; ATPM; hATP1; OMR; ORM; COXPD22; HEL-S-123m; MC5DN4; MC5DN4A; MC5DN4B; MOM2
Tractability: Small molecule: a structure with a bound ligand is known. Antibody: UniProt places it where antibodies can reach, with high confidence; its Gene Ontology location is reachable by antibodies, with high confidence. PROTAC: ubiquitination databases record sites on it.
Target class: Enzyme; Hydrolase
Gene: Protein-coding gene on chromosome 18 (46,080,248 to 46,104,334, reverse strand). Ensembl gene ENSG00000152234.
Subcellular location: Mitochondrion; Mitochondrion inner membrane; Cell membrane
Subcellular location (Human Protein Atlas): Mitochondria; End piece
Pathways (Reactome):
Metabolism: Formation of ATP by chemiosmotic coupling
Metabolism of proteins: Mitochondrial protein degradation
Organelle biogenesis and maintenance: Cristae formation
Protein localization: Mitochondrial protein import
Gene Ontology:
Molecular function: angiostatin binding; MHC class I protein binding; protein binding; proton-transporting ATP synthase activity, rotational mechanism; RNA binding; ADP binding; ATP binding; adenyl ribonucleotide binding; ATP hydrolysis activity; protease binding
Biological process: ATP biosynthetic process; negative regulation of endothelial cell proliferation; positive regulation of blood vessel endothelial cell migration; proton motive force-driven ATP synthesis; proton motive force-driven mitochondrial ATP synthesis; lipid metabolic process; ATP metabolic process; cellular response to dexamethasone stimulus; cellular response to nitric oxide; proton transmembrane transport; response to ethanol; response to muscle activity
Cellular component: extracellular exosome; membrane; mitochondrial inner membrane; mitochondrion; plasma membrane; proton-transporting ATP synthase complex; mitochondrial matrix; cell surface; membrane raft; proton-transporting two-sector ATPase complex; transmembrane transporter complex
Genetic constraint (gnomAD): Loss-of-function variants: 24 observed, 58.55 expected, observed/expected ratio (o/e) 0.41, 90% interval 0.3 to 0.58. The upper end of that interval is the gene's LOEUF score, 0.58, which puts it in group 2 of 6, group 1 being the genes least tolerant of losing a copy. Missense variants: 494 observed, 727.39 expected, observed/expected ratio (o/e) 0.68, 90% interval 0.63 to 0.73. Synonymous variants: 251 observed, 259.84 expected, observed/expected ratio (o/e) 0.97, 90% interval 0.87 to 1.07.
Homologues: Orthologues: chimpanzee ATP5F1A (100% identical), dog ATP5F1A (98% identical), mouse Atp5f1a (97% identical), macaque ATP5F1A (97% identical), rat Atp5f1a (97% identical), pig ATP5F1A (95% identical), guinea pig ATP5F1A (93% identical), tropical clawed frog atp5f1a (93% identical), zebrafish atp5fa1 (91% identical), Drosophila melanogaster blw (82% identical), Caenorhabditis elegans T26E3.7 (10% identical). Paralogues in human: ATP6V1B2 (24% identical), ATP6V1B1 (22% identical), ATP5F1B (22% identical), ATP6V1A (18% identical).
Diseases named in the same sentence as ATP5F1A in open-access papers:
ATP5F1A is named in the same sentence as 71 diseases in open-access papers, as found by Europe PMC text mining. Sharing a sentence is not in itself a finding about the gene and the disease. The quoted sentences say what the papers report.
Parkinson disease (6 papers, 2018 to 2025). A progressive degenerative disorder of the central nervous system characterized by loss of dopamine producing neurons in the substantia nigra and the presence of Lewy bodies in the substantia nigra and locus coeruleus. "For example, FV-derived fucoidan has been shown to alleviate mitochondrial dysfunction and prevent dopaminergic neuron loss in a Parkinson’s disease mouse model, effects mediated via the regulation of ATP5F1a, a key mitochondrial protein." (PMID 40863639, 2025).
prostate carcinoma (5 papers, 2018 to 2025). A carcinoma that arises from epithelial cells of the prostate gland. "Targeting key autophagic signaling pathways, such as TNK2/ACK1-mediated phosphorylation of ATP5F1A, can hinder prostate cancer progression by promoting mitophagy and reducing tumor growth." (PMID 39409882, 2024). "The analysis of truncation of SFT2D2‐TBX19 and structural domain of ATP5F1A offers insights into its potential as a target for chemotherapy in prostate cancer." (PMID 39540264, 2024). "This research provides comprehensive evidence that chimeric SFT2D2‐TBX19 promotes prostate cancer progression by encoding the TBX19‐202 protein and stabilizing mitochondrial ATP synthase via ATP5F1A phosphorylation." (PMID 39540264, 2024). "A possible role of complex V in prostate cancer development is suggested by the significant positive correlation of ATP5F1A levels with earlier-onset prostate cancer (age at diagnosis and at prostatectomy) and free PSA percentage." (PMID 30538797, 2018). "In addition, phosphorylation of ATP5F1A at Y243/246 can maintain high mitochondrial output, and this mechanism is activated in prostate cancer, suggesting that posttranslational modification of ATP5F1A has a potentially powerful regulatory role in diseases." (PMID 40800583, 2025). "Overall, the level of complex V subunit ATP5F1A was increased in our prostate cancer cohort." (PMID 30538797, 2018). "Indeed, a possible role of complex V in prostate cancer development is also suggested by the significant positive correlation we detected between ATP5F1A level and age at diagnosis/prostatectomy as well as ATP5F1A level and percentage of free PSA in relationship to total PSA." (PMID 30538797, 2018). "Prostate cancer cell proliferation, migration and invasion were reversed in the SFT2D2‐TBX19 overexpression group following ATP5F1A or ATP5F1B knockdown." (PMID 39540264, 2024).
Alzheimer disease (4 papers, 2018 to 2025). A progressive, neurodegenerative disease characterized by loss of function and death of nerve cells in several areas of the brain leading to loss of cognitive function such as memory and language. "Although this study did not directly assess ATP5F1A acetylation levels, our proteomic analysis revealed significantly elevated lactylation levels of the mitochondrial metabolic enzyme phosphoglycerate kinase 1 (PGK1) in Alzheimer’s disease tissues." (PMID 40800583, 2025).
breast carcinoma (3 papers, 2020 to 2023). "Overall, we propose that targeting the AURKA/ATP5F1A/ATP5F1B nexus is a promising avenue to lower breast cancer cell metabolism and reduce cell proliferation." (PMID 37386025, 2023). "Several studies have demonstrated that ATP5F1A is overexpressed in breast carcinoma cell lines with different metastatic potential." (PMID 35805203, 2022). "Altogether, these results indicate that AURKA, ATP5F1A, and ATP5F1B cooperate in regulating cell cycle progression and in maintaining total ATP levels in breast cancer cells with high AURKA expression." (PMID 37386025, 2023). "After observing that AURKA is at a FRET-compatible distance with ATP5F1A and ATP5F1B, we asked whether these proteins could be a nexus regulating cell cycle progression and ATP levels in breast cancer cells." (PMID 37386025, 2023).
colorectal cancer (3 papers, 2020 to 2024). A primary or metastatic malignant neoplasm that affects the colon or rectum. "Inhibition of ATP5F1A has been shown to increase colorectal cancer cell proliferation, while its low expression correlates with poor prognosis in colorectal cancer patients." (PMID 38577591, 2024).
COVID-19 (3 papers, 2021 to 2023). A disease caused by infection with severe acute respiratory syndrome coronavirus 2. "Interestingly, we also found that ATP synthesis-related genes (e.g., ATP5F1A, ATP5F1B, ATP5F1C, ATP5F1D, ATP5F1E) were significantly increased in COVID-19 patients." (PMID 37087411, 2023).
glioblastoma (3 papers, 2020 to 2024). The most malignant astrocytic tumor (WHO grade IV). "AURKA is a key factor in the pathogenesis of glioblastoma, and increased levels of ATP5F1A and ATP5F1B were observed in glioblastoma models and are accompanied by an upregulation of oxidative metabolism." (PMID 37386025, 2023).
cognitive decline (1 paper, 2025). "For AD, ATP5F1A (Importance 17.7), a mitochondrial ATP synthase subunit critical for energy production, was associated with Aurovertin B (PUBCHEM_CID: 444853), an F1F0-ATPase inhibitor that could modulate ATP synthesis in cognitive decline." (PMID 40864790, 2025).
developmental delay (1 paper, 2025). "We identified a patient with developmental delay, myoclonic dystonia, and spasticity who carried a heterozygous frameshift c.1404del (p.Glu469Serfs*3) variant in ATP5F1A." (PMID 40276935, 2025).
Dystonia (1 paper, 2025). An abnormally increased muscular tone that causes fixed abnormal postures. "In this study, we have gathered a set of five patients from four unrelated families with autosomal dominant variants in ATP5F1A or ATP5F1B, further defining the genetic, molecular, and phenotypic profile of ATPase‐related diseases with dystonia and spasticity." (PMID 40276935, 2025). "Our observations underscore the importance of anticipating a broad phenotypic spectrum for such potential molecular alterations in ATP5F1A/ATP5F1B‐related conditions, ranging from isolated or complex dystonia to HSP and CP." (PMID 40276935, 2025).
triple-negative breast carcinoma (1 paper, 2023). An invasive breast carcinoma which is negative for expression of estrogen receptor (ER), progesterone receptor (PR), and human epidermal growth factor receptor 2 (HER2). "Last, we discover that the roles of the AURKA/ATP5F1A/ATP5F1B nexus depend on the specific metabolic propensity of triple-negative breast cancer cell lines, where they correlate with cell fate." (PMID 37386025, 2023). "Altogether, these data further support the direct role of AURKA, ATP5F1A, and ATP5F1B within a potential metabolic nexus in triple-negative breast cancer cells." (PMID 37386025, 2023).
tumor (18 papers, 2006 to 2026). "Another study reported the reduced expression of NDUFS4, SDHA, UQCR2, MT-CO1, and ATP5F1A in tumor samples from 94 PCa patients who had undergone radical prostatectomy after tumor diagnosis." (PMID 36901912, 2023). "In the present study, the levels of SDHA, UQCRC2, MT-CO1 and ATP5F1A were significantly reduced in the tumor periphery compared to the control tissue." (PMID 31167495, 2019). "Here, we uncover a previously unrecognized role of Bacteroides intestinalis in restraining extra-intestinal tumor growth via OMVs enriched in sphingosine (SP), a bioactive lipid that directly binds to ATP5F1A-a subunit of the mitochondrial ATP synthase-to enhance NK cell function." (PMID 41972457, 2026). "Collectively, we hypothesize that ASB6-mediated ubiquitination and degradation of ATP5F1A suppresses oxidative phosphorylation and enhance glycolysis to facilitate tumor progression." (PMID 38577591, 2024). "Finally, ATP5F1A (subunit of complex V/ATP synthase) was significantly diminished in the tumor periphery (p < 0.001) and showed a trend to lower levels in the center, compared to controls." (PMID 31167495, 2019).
cancer (9 papers, 2018 to 2025). A tumor composed of atypical neoplastic, often pleomorphic cells that invade other tissues. "Our work paves the way to novel anti-cancer therapies targeting the AURKA/ATP5F1A/ATP5F1B nexus to lower cancer cell metabolism and proliferation." (PMID 37386025, 2023). "Since AURKA-specific inhibitors show poor efficacy and a high degree of toxicity in clinical trials, the available inhibitors against Complex V functions could be a valuable resource for combinatorial therapies against AURKA and ATP5F1A or ATP5F1B in AURKA-related cancers in the upcoming future." (PMID 37386025, 2023). "ATP5F1A deficiency was never observed in both carcinoma and adjacent benign prostate tissue." (PMID 30538797, 2018). "Last, our data suggest that ATP5F1A and ATP5F1B could be promising targets in AURKA-overexpressing cancers." (PMID 37386025, 2023). "Similarly, some progressors (CHMP4B, CSTF1, and LSM14B) and suppressors RBPs (ATP5F1A, GTF2E2, RTF1, ELAC2, LRRC47, and MRM3) have never been associated with COAD or READ, but present oncogenic properties in other cancer types." (PMID 37384253, 2023).
neurodegenerative disease (3 papers, 2022 to 2025). A disorder of the central nervous system characterized by gradual and progressive loss of neural tissue and neurologic function. "IF regulates lipid metabolism primarily via genes including FABP4, WNT10B, PCK1, PLIN1, LEPR, and ADIPOQ, providing energy for cold adaptation, whereas PF positively influences in vivo degenerative diseases mainly through genes such as ATP5F1A, ATP5PO, SDHB, NDUFS8, SDHA, and COX5A." (PMID 40136641, 2025). "In contrast, in PF tissue, genes like ATP5F1A, ATP5PO, SDHB, NDUFS8, SDHA, and COX5A play roles within the neurodegenerative disease pathway, and PF tissue has a positive impact on the process related to degenerative diseases." (PMID 40136641, 2025).
mitochondrial disease (1 paper, 2025). "Mutation or deletion in ATP5F1A may lead to serious mitochondrial diseases and pose a considerable threat to the motor and nervous systems." (PMID 40800583, 2025).
movement disorder (1 paper, 2025). Neurological conditions resulting in abnormal voluntary or involuntary movement, which may impact the speed, fluency, quality and ease of movement. "The aim of this study was to redefine the phenotypic and mutational spectrum of movement disorders linked to the ATPase subunit‐encoding genes ATP5F1A and ATP5F1B." (PMID 40276935, 2025). "Disease‐related ATP5F1A/ATP5F1B alleles implicated in movement disorders to date were monoallelic missense variants, variably causing compromised ATPase activity and/or reductions in subunit expression levels." (PMID 40276935, 2025). "Overall, this study confirms heterozygous variants in ATP5F1A and ATP5F1B as an underreported cause of a wider range of neurological phenotypes with prominent movement disorders and permits the determination of an expanded mutational spectrum." (PMID 40276935, 2025).
ATP5F1A also shares sentences with these, for which no sentence is quoted: Sepsis (5 papers); clear cell renal cell carcinoma (4); colon cancer (4); Mitochondrial encephalopathy (4); ischemia (3); myocarditis (3); adenoma (2); colon adenocarcinoma (2); melanoma (2); neurodevelopmental disorder (2); neurological diseases (2); schizophrenia (2); sleep disorder (2); type-2 diabetes (2); acute myocardial infarction (1); adenocarcinoma (1); amyotrophic lateral sclerosis (1); Aortic dissection (1); Atrophy (1); bipolar disorder (1); brain diseases (1); cardiomyopathy (1); chronic lymphocytic leukemia (1); Cirrhosis (1); combined oxidative phosphorylation deficiency 22 (1); depression (1); diabetic cardiomyopathy (1); Encephalopathy (1); gastric cancer (1); gestational diabetes (1).
A further 25 diseases each share a sentence with ATP5F1A in 1 paper.